APOE (apolipoprotein E)
Diseases named in the same sentence as APOE in open-access papers (continued):
Sharing a sentence is not in itself a finding about the gene and the disease.
Lewy body dementia (continued). "Of particular interest is apolipoprotein E (APOE), variants of which can increase risk for developing late-onset AD (LOAD) and Lewy body dementia." (PMID 37577533, 2023). "Previous studies have found that in PD and other Lewy body diseases, apoE expression occurs in substantia nigra neurons and Lewy bodies, and the expression of apoE receptors is significantly increased." (PMID 35801143, 2022). "The apoE-cholesterol pathway differentially affects both AD and Lewy Body dementia (LBD), and the relevance of cholesterol in Lewy Body pathology has been recently reviewed." (PMID 36153580, 2022). "Many recent GWAS have reported genomic variants, including GBA, APOE, SNCA, and CNTN1 that are associated with dementia with Lewy bodies (DLB)." (PMID 34946922, 2021). "Postmortem brains from Lewy body disease carrying APOE4 also show increased apoE accumulation in Lewy bodies." (PMID 34453582, 2021). "Nonetheless, since it has been reported that Aβ plaques could promote seeding and spreading of αSyn in a mouse model of Lewy body dementia with Aβ pathology, further studies are needed to investigate how APOE and Aβ impact αSyn pathology under disease conditions." (PMID 34453582, 2021). "Their findings suggest that the impact of the APOE ε4 allele might be more pronounced in the neocortex, where AD and Lewy body disease pathologies are found, rather than in the subcortical and brainstem structures where Lewy bodies are predominantly found in PD." (PMID 38026513, 2023). "The progress of those with ApoE ε3/ε4 was interrupted by intercurrent conditions, lack of supplementation, or a new diagnosis (Lewy body disease and multi-infarct dementia)." (PMID 27677546, 2017). "In addition, APOE is related to non-AD neuropathological alterations, such as Lewy body dementia (LBD) characterized by aggregates of the α-synuclein protein and limbic-predominant age-related TAR DNA-binding protein 43 (TDP-43) encephalopathy." (PMID 38115150, 2023). "While many studies have shown that APOE ε4 is associated with Lewy body dementia, it should be noted that a recent study did not confirm the involvement of APOE ε4 in DLB without AD pathology." (PMID 41185066, 2025).
abdominal aortic aneurysm (65 papers, 2009 to 2025). Enlargement and ballooning of the vessel that supplies arterial blood to the abdomen, pelvis and legs. "Metformin, a biguanide antihyperglycemic agent, prevents angiotensin II (AngII)-induced abdominal aortic aneurysm formation in apolipoprotein E-deficient (ApoE−/−) mice." (PMID 40502134, 2025). "Abdominal aortic aneurysms (AAAs) were created by angiotensin II infusion in ApoE-deficient mice (n = 9)." (PMID 34580810, 2022). "Rivaroxaban treatment (15 mg/kg/d) can significantly reduce the maximal aortic diameter and suppress experimental abdominal aortic aneurysm progression in ApoE-deficient (ApoE-/-) mice." (PMID 35762638, 2022). "Adams and colleagues aimed to assess the risk of rupture of abdominal aortic aneurysms (AAA) caused by increased vascular permeability in ApoE-/--mice." (PMID 34681063, 2021). "For example, apolipoprotein E-deficient mice (Apoe−/− mice) infused with angiotensin II can only form abdominal aortic aneurysm or dissection." (PMID 33066131, 2020). "The study is aimed at exploring the role of the P2Y6 receptor in Ang II-induced abdominal aortic aneurysm (AAA) formation in apolipoprotein E-deficient (apoE−/−) mice by using its selective antagonist." (PMID 32382533, 2020). "Angiotensin II (Ang II) infusion into ApoE−/− mice augments atherosclerotic plaque and abdominal aortic aneurysm (AAA) formation, via mechanisms causing increased monocyte-macrophage recruitment and vascular wall remodeling." (PMID 30048944, 2018). "An animal model commonly used to investigate pathways and potential therapeutic interventions relevant to abdominal aortic aneurysm (AAA) involves subcutaneous infusion of angiotensin II within the apolipoprotein E deficient mouse." (PMID 19580648, 2009). "Moreover, in angiotensin II-treated apolipoprotein E (ApoE), GrB deficiency was associated with decreased abdominal aortic aneurysms and increased survival (because of rare aneurism rupture) compared to perforin-deficient or control mice." (PMID 33262766, 2020). "Additional work indicated that deficiency of endogenous APOE could protect mice from angiotensin II-induced abdominal aortic aneurysm formation." (PMID 29042594, 2017). "Consistent result have also been detected in abdominal aortic aneurysm model in ApoE–/–OPN–/–mice characterized by impaired leukocyte recruitment and cell migration." (PMID 38426091, 2024). "In the present study, we demonstrated that baicalein suppressed abdominal aortic aneurysm formation in Ang II-induced ApoE−/− mice." (PMID 37958985, 2023). "This study evaluated the effects of IL-22 on AD/abdominal aortic aneurysm (AAA) formation in angiotensin II (Ang II)-infused ApoE-/- mice." (PMID 35340206, 2022). "A mouse abdominal aortic aneurysm model wasestablished by embedding an Ang II pump (1000 ng/kg/min) in ApoE-/- mice.Ang II activated monocytes to express CXCR2(CD45+CD11+bF4/80+) during AAA formation." (PMID 33605308, 2021). "Our previous study also demonstrated that Alda-1 attenuated AngII-induced abdominal aortic aneurysm (AAA) in ApoE-KO mice." (PMID 34764958, 2021). "The level of IL-6 was increased in the vessel wall of abdominal aortic aneurysms in AngII-infused ApoE-/- mice compared to similar sections of aorta in saline-infused control mice." (PMID 32362823, 2020). "We used experimental abdominal aortic aneurysm models: Angiotensin II (Ang II)–induced ApoE−/− male mice (Ang II/APOE model) in our study." (PMID 32982758, 2020). "The continuous angiotensin II infusion in ApoE-/- mice resulted in the development and progression of abdominal aortic aneurysms." (PMID 28582441, 2017). "The results conclude that oral administration of sitagliptin can prevent abdominal aortic aneurysm formation in Ang II-infused apoE-/-mice, at least in part, by increasing of GLP-1 activity, decreasing MMP-2 and MMP-9 production from macrophage infiltration." (PMID 25876091, 2015).
abdominal aortic aneurysm (continued). "In ApoE-/-, angiotensin II-infused mice, abdominal aortic dissection was found to precede the formation of abdominal aortic aneurysms." (PMID 25398022, 2014). "Angiotensin II (ANG II) promotes vascular inflammation and induces abdominal aortic aneurysm (AAA) in hyperlipidemic apolipoprotein E knock-out (apoE−/−) mice." (PMID 22448249, 2012). "Moreover, nuclear membrane, nucleolar, and nucleoplasm genes are upregulated in apolipoprotein E deficient (ApoE–/–) atherosclerotic aortas and in AngII-induced abdominal aortic aneurysm (AAA) in ApoE–/– mice." (PMID 40919531, 2025). "In addition, a recent study noted that knockdown of PVT1 decreased levels of MMP-2 and MMP-9, augmented TIMP-1 expression, and suppressed serum levels of TNF-α, IL-1β, and IL-6 in VAMC and ApoE-/- mice of abdominal aortic aneurysm model." (PMID 34775377, 2021). "In this study, the ApoE−/− mouse, a common model of abdominal aortic aneurysm, was used." (PMID 34007253, 2021). "Recently, it has been shown that in ApoE gene-knockout mice with abdominal aortic aneurysms, infusion of ANG II for 4 weeks increased expression of class I HDAC1, 2, and 3, as well as expression of class II HDAC 4 and 7; it also decreased acetylation levels of H3-K1873." (PMID 32152395, 2020). "Furthermore, we revealed that β5i is involved in the modulation of the infiltration of proinflammatory cells into abdominal aortic aneurysm and atherosclerotic lesion, as well as vascular remodeling in ApoE knockout mice." (PMID 32848742, 2020). "The role of Non‐POU‐domain‐containing octamer‐binding protein (NONO) in the formation and development of angiotensin II (Ang II)‐induced abdominal aortic aneurysm (AAA) in apolipoprotein E‐knockout (ApoE−/−) mice is still unknown." (PMID 31512366, 2019). "After 4-week Ang II infusion, obvious abdominal aortic aneurysm was developed in ApoE−/− mice." (PMID 28369137, 2017). "illustrated that Ctss expression was profoundly elevated in abdominal aortic aneurysm (AAA) lesions of mice models, and that the incidence of AAA in ApoE–/– Ctss–/– mice (10%) was significantly lower compared to ApoE–/– Ctss+/+ mice (80%)." (PMID 34077394, 2021). "After infusion with Ang II or saline for 28 days, no abnormal aortic morphology or spontaneous abdominal aortic aneurysm (AAA) was found in the saline-treated ApoE−/− Nox1y/fl and ApoE−/−Nox1SMCko mice." (PMID 39721498, 2025). "Similarly, in a mouse model of abdominal aortic aneurysm, levels of several HETEs (5-, 8-, 12-, 15-HETE) were similar in the blood of wildtype and APOE knockout mice, and were higher in APOE knockout mice after pro-coagulant administration." (PMID 34604280, 2021). "Ginsenoside Rb1, but not Rg1, suppressed abdominal aortic aneurysm (AAA) in Ang II-infused ApoE−/− mice through inhibiting JNK and p38 signaling pathways." (PMID 31623159, 2019). "Simvastatin has been reported to inhibit AAA formation induced by angiotensin II (AngII) in apolipoprotein E knockout (Apoe−/−) mice, while rosuvastatin and atorvastatin had no benefit for abdominal aortic aneurysms." (PMID 28179583, 2017).
dysbetalipoproteinemia (61 papers, 2007 to 2026). "APOE E2 is associated with type III hyperlipoproteinemia, has been linked to increased malaria infections and severity in early childhood, and has been observed to be associated with reduced reproductive efficiency." (PMID 40323280, 2025). "In dysbetalipoproteinemia (formerly Type 3 hyperlipoproteinemia), patients carry a further ApoE2 homozygosity or a rare binding-defective dominant mutation in ApoE, leading to impaired hepatic clearance of remnant lipoproteins." (PMID 41012446, 2025). "Familial dysbetalipoproteinemia (FD) is a prevalent and highly atherogenic hyperlipoproteinemia associated with the ε2/ε2 APOE genotype or rare APOE variants." (PMID 40806502, 2025). "The APOE-Christchurch (APOECh) variant was first discovered in 1987 in an APOE2 patient with type III hyperlipoproteinemia." (PMID 39169951, 2024). "Familial dysbetalipoproteinemia (FDBL) is most frequently determined by homozygous recessive mutations of the E2 allele of the apolipoprotein E (APOE) gene (located on chromosome 19q13.32)." (PMID 37510094, 2023). "Variants in APOE gene are usually associated with dysbetalipoproteinemia; however, a rare APOE deletion have been reported to be associated to FH." (PMID 38122934, 2023). "Dysbetalipoproteinemia is a rare genetic disease caused by a homozygous mutation in the gene encoding for apolipoprotein E (ApoE)." (PMID 36904088, 2023). "APOE mutations are an important determinant of lipid profiles and cardiovascular health in the population and can precipitate dysbetalipoproteinemia and glomerulopathy." (PMID 35602473, 2022). "Familial dysbetalipoproteinemia (FDBL) is due to autosomal homozygous recessive E2 allele in the apolipoprotein E (ApoE) gene, or in ~10% of FDBL cases, a dominant E3 or E4 allele." (PMID 34146174, 2021). "Because the APOE ε2 genotype has been associated with type III hyperlipoproteinemia and is linked to cardiovascular health, we also evaluated cardiovascular comorbidities, and these did not markedly change the results." (PMID 33748669, 2021). "APOE variants are associated with autosomal dominant and multifactorial inheritance of type 3 hyperlipoproteinemia." (PMID 30026549, 2018). "Deficiency of APOE or mutation in APOE that inactivates its binding capacity to lipoprotein receptors can cause type III hyperlipoproteinemia (HLP)." (PMID 29099857, 2017). "The functional deficiency of ApoE protein contributes to the risk of familial dysbetalipoproteinemia or type III hyperlipoproteinemia (HLP III)." (PMID 28465483, 2017). "The human ApoE protein has Arg (encoded by UGC) instead of Cys residues associated with type 3 hyperlipidemia." (PMID 25006576, 2014). "Since researchers first described the effects of apoE polymorphism on dysbetalipoproteinemia, a considerable amount of studies have explored the association between apoE gene and CHD risk in the general population." (PMID 24755673, 2014). "One PXE patient was even characterized by a homozygous ε2 isoform of APOE, which can be a risk factor for type III hyperlipoproteinemia in 5- 10% of ε2 homozygous carriers." (PMID 25064003, 2014). "Type III dysbetalipoproteinemia diagnosis, a rare inherited disorder caused by ApoE (commonly ApoE2) defective binding to lipoprotein receptor, is however an exception." (PMID 25071563, 2014). "Thus, ApoE gene transfer can be used to treat hyperlipoproteinemia type III, which is caused by the presence of specific ApoE isoforms." (PMID 40725196, 2025). "APOE, as a core component of plasma lipoproteins, is involved in their production, conversion, and clearance and is associated with lipoprotein glomerulopathy and hyperlipoproteinemia type III." (PMID 39050255, 2024). "The phenotype of ApoE-deficient mice includes a hyperlipidemic plasma profile with disrupted hepatic uptake of both liver- and intestine- derived ApoB-containing lipoproteins, thus resembling human hyperlipoproteinemia type III." (PMID 29438441, 2018).
dysbetalipoproteinemia (continued). "The APOE ɛ2ɛ2 haplotype that predisposes to type III hyperlipoproteinemia, was observed in three FCH family members (two of them affected), all with elevated cholesterol and TG concentrations in very low-density lipoprotein and intermediate-density lipoprotein fractions." (PMID 27227539, 2016). "The primary variations in the APOE gene are caused by alleles that translate different protein isoforms that are only differentiated by a single amino acid substitution at positions 112 and 158: The ApoE-ε2 isoform (Cis112Cis158) has been linked to the manifestation of hyperlipoproteinemia type III." (PMID 38607741, 2024). "Whether APOE variants are the cause of FH or dysbetalipoproteinemia remains to be discussed." (PMID 38122934, 2023). "Familial dysbetalipoproteinemia (FD), also known as type III hyperlipoproteinemia (OMIM #617347), is a genetically determined lipid disorder primarily linked with APOE gene variants." (PMID 40806502, 2025). "Familial dysbetalipoproteinemia (FD), also known as hyperlipoproteinemia type III (OMIM #617347), is a genetically based lipid disorder caused by variants in the APOE gene." (PMID 37685967, 2023). "It is well known that all patients with type III hyperlipidemia (dysbetalipoproteinemia) were APOE ε2 homozygous, whereas most ε2/ε2 subjects (>90%) were normolipidemic or even hypolipidemic, owing to reductions in LDL or HDL or both." (PMID 35154509, 2022). "Mutations in mouse ApoE result in human-like phenotypes, such as hyperlipoproteinemia type III, xanthomatosis, or dysbetalipoproteinemia." (PMID 32714944, 2020). "Defects in ApoE lead to familial dysbetalipoproteinemia, also known as type III hyperlipoproteinemia, where elevated levels of cholesterol and TGs in blood plasma are caused by disrupted clearance of chylomicrons, very LDL, and LDL." (PMID 32121175, 2020). "Mutations in the 136–150 region of the N-terminal domain of apoE, reduce its low density lipoprotein (LDL) receptor binding capacity and have been linked with lipoprotein disorders, such as type III hyperlipoproteinemia (HLP) in humans." (PMID 22069485, 2011). "Consistent with this hypothesis was the observation that subjects with lysine-to-glutamate mutation within the receptor binding domain, at residue 146, of apoE, displayed a dominant dysbetalipoproteinemia phenotype with an early age onset." (PMID 36077289, 2022). "ApoE is a ligand for both LDL receptor and LRP and plays an important role in the catabolism of remnant lipoproteins in the liver and genetic deficiency of apoE is a cause of human type III hyperlipoproteinemia." (PMID 33603774, 2021). "Patients with LPG have proteinuria and nephrotic syndrome with elevated serum APOE levels, abnormal lipoprotein deposition in glomerular capillaries in form of laminated thrombi that contain APOB and APOE, a variable degree of mesangial proliferation, and dysbetalipoproteinemia." (PMID 25352833, 2014). "ApoE, associated with HDL, is a main lipoprotein of the chylomicron and is involved in the catabolism of triglyceride-rich lipoprotein constituents; defects in the gene encoding this protein result in familial dysbetalipoproteinemia (NCBI: APOE, 2011)." (PMID 22994408, 2012). "The findings from our literature study further support a causal connection between pathogenic homozygous and heterozygous rare variants in APOE, with a significant negative impact on APOE function and the presenting phenotype (dysbetalipoproteinemia and splenomegaly)." (PMID 40149441, 2025). "Thus, according to the number or the nature of these factors, APOE variants could be associated with the overlapping phenotypes of FCHL, ADH, and sometimes familial dysbetalipoproteinemia when the subject is E2/E2." (PMID 35628605, 2022).
dysbetalipoproteinemia (continued). "Patients with type III hyperlipoproteinemia, or Familial Dysbetalipoproteinemia (FD), show elevated levels of TC and TG, usually in the range of 300–500 mg/dL (3.39–5.65 mmol/L), derived from increased plasma levels of chylomicron and VLDL remnants enriched in cholesterol esters and apoE." (PMID 36979789, 2023). "Thus, from a lipoprotein point of view, brown bears seem to resemble dysbetalipoproteinemia (type III), but the absence of apoE and apoB48 makes their LDL size/density lipoproteins to become not atherogenic (the latter prevents a condition similar to an ApoE knockout)." (PMID 33713671, 2021).